TNF (tumor necrosis factor)
Diseases named in the same sentence as TNF in open-access papers (continued):
Sharing a sentence is not in itself a finding about the gene and the disease.
schizophrenia (continued). "These pioneering findings were replicated in later studies, which additionally showed immune-inflammatory processes in the CNS and associations between schizophrenia and immune genes, including single nucleotide polymorphisms in tumor necrosis factor (TNF)-α." (PMID 34831151, 2021). "The review also commented that prenatal exposure to inflammatory molecules, especially tumor necrosis factor (TNF), also contributes to schizophrenia risk." (PMID 34884840, 2021). "High circulating maternal TNF has been associated with increased risk of schizophrenia and severity of autism spectrum disorder in individuals exposed in utero." (PMID 34582452, 2021). "Our results indicated that neuroinflammation along with peripheral TNF-α elevation is associated with schizophrenia-relevant behaviors in amphetamine-sensitized mice." (PMID 32341334, 2020). "With regard to schizophrenia, the Th17 signaling pathway, IL-6, and TNF-α are also associated with the development and aggravation of schizophrenia." (PMID 32987907, 2020). "Positive association has also been found between TNF-α-G308A functional polymorphism and schizophrenia." (PMID 31642026, 2020). "Regarding the specific immune markers, TNF, a pro-inflammatory cytokine, and IL-10, an anti-inflammatory cytokine, were associated with slowed task performance in patients with schizophrenia." (PMID 32238816, 2020). "For example, the polymorphisms of interleukin (IL) -10, IL-6 and tumor necrosis factor α (TNF-α) are related to a high risk of developing schizophrenia and their levels in blood are higher in schizophrenia patients compared with healthy subjects." (PMID 30792621, 2019). "The CTGG haplotype build with tested SNPs of TNFR2 and SNP-308G/A of TNF-α was associated with an increased risk of schizophrenia in men and a reduced risk in women." (PMID 30254506, 2018). "First, genotypes of -308G/A SNP of TNF-α gene showed the sex differences in predisposition to schizophrenia." (PMID 30254506, 2018). "Increased tumor necrosis factor (TNF)-α in late pregnancy has also been linked to schizophrenia in the offspring." (PMID 30225350, 2018). "Association of studies of -308G/A TNF-α polymorphism with schizophrenia has produced discrepant results." (PMID 30254506, 2018). "The CTGG haplotype build with tested SNPs of TNFR2 and SNP -308G/A of TNF-α has an association with a risk of schizophrenia in Caucasian population depending on sex." (PMID 30254506, 2018). "In the current analysis, we showed that the haplotype build with polymorphism variants of TNFR2 and TNF-α has an association with the risk of paranoid schizophrenia in Caucasian population depending on sex." (PMID 30254506, 2018). "Elevated pro-inflammatory cytokines such as interleukin (IL)-1, IL-6, CRP and tumor necrosis factor alpha (TNF-α), are known as common pathogenic parts of schizophrenia, ADHD and autism." (PMID 28700674, 2017). "While the underlying cause of the cytokine dysregulation we have found here is not known, decreased IL-2, increased IL-6, IL-8 and TNFα have all been associated with Toxoplasma gondii infections, of which the seroprevelance is increased in schizophrenia." (PMID 28923068, 2017). "A study investigating a population of carriers of the NRG1 (valine to leucine) mutation has observed increased circulating proinflammatory cytokines, including IL-6, TNF-α, and IL-1b suggesting a role of this mutation in immune dysregulation in schizophrenia." (PMID 23805069, 2013). "Second, increased maternal levels of the pro-inflammatory cytokine tumor necrosis factor-α (TNF-α) and the chemokine interleukin-8 during pregnancy have been directly associated with a higher risk for schizophrenia in the progeny." (PMID 22208616, 2011). "A functional single nucleotide polymorphism within the promoter region of the TNF-α gene, has been related to the pathogenesis of several diseases, including Schizophrenia." (PMID 19506720, 2008).
schizophrenia (continued). "The gene that encodes TNF-α is mapped to chromosome 6p21.3–p21.1, a region linked in several studies to Schizophrenia." (PMID 19506720, 2008). "More specifically, emerging data demonstrate associations between schizophrenia and genetic polymorphisms in regulators of inflammation such as tumor necrosis factor alpha genes and interleukin-1 genes." (PMID 15707482, 2005). "Additionally, elevated sTNFR1 and TNF have been associated with worse clinical functioning in individuals with schizophrenia and bipolar disorder." (PMID 41567988, 2026). "The elevated production of tumor necrosis factor (TNF) observed in preeclampsia is thought to influence neuroglial processes and synaptogenesis, further contributing to the risk of psychiatric disorders such as schizophrenia." (PMID 40572764, 2025). "Additionally, increased concentrations of IL-1β, IL-6, IL-10, IL-17, and sIL-2, and a reduction in TNF-α are associated with more severe positive symptoms of schizophrenia." (PMID 40364201, 2025). "The link between inflammation and psychiatric disorders has also been found in CCBs, which might increase TNF-a, an inflammatory factor and inflammation may be associated with schizophrenia." (PMID 38166843, 2024). "In addition, a number of clinical trials have shown that the administration of olanzapine to patients with schizophrenia causes an increase in plasma cytokines like TNF-α, IL-6, and IL-1." (PMID 38292473, 2024). "TNF-α has an established role in the inflammatory response and has been associated with various psychiatric symptoms, such as affective symptoms and cognitive function, as well as being involved in the etiology of the acute and chronic phases of schizophrenia." (PMID 38429778, 2024). "In addition, TNF-alpha polymorphisms have been associated with an earlier age of first SA in individuals with schizophrenia and with SA in depressed patients (Y. K)." (PMID 38737407, 2024). "Nevertheless, H2S may affect the production of local regulatory factors, including cytokines IL-1 and TNF-α and cause various structural modifications of receptor molecules, which may be at least theoretically related to the pathogenesis of schizophrenia." (PMID 37874531, 2023). "Furthermore, aside from BDNF, other inflammatory factors such as IL-6 and TNF and the complement system are associated with neurodevelopment and schizophrenia, and their correlation analysis with the age of young children needs to be investigated further." (PMID 37234686, 2023). "Finally, endothelial cells have been shown to be involved in TSPO modulation in a model of acute inflammation induced by an adeno-associated virus encoding the tumor necrosis factor gene or in schizophrenia." (PMID 37408083, 2023). "Furthermore, poor cognitive functioning and disability in daily life activities are negatively associated with increased peripheral TNF-α and IL-12p70 levels in patients with schizophrenia." (PMID 35887634, 2022). "This gives plausibility to the theory that the microglial activation seen in schizophrenia patients could be caused by LPS and TNF-α traveling via the circulatory system." (PMID 35844244, 2022). "If a schizophrenia patient experiences chronic stress, an increased production of pro-inflammatory cytokines such as TNF-α could cause significant damage." (PMID 35844244, 2022). "High levels of Interleukin (IL)-1, IL-6, IL-8, and tumor necrosis factor (TNF)-α could affect the development of the fetal brain and circulatory system, and might increase the risk of schizophrenia, autism, and mental disorders." (PMID 33710249, 2021). "A study on 2512 patients with schizophrenia indicated that the TNF-α A allele may have an impact on susceptibility to schizophrenia." (PMID 34763685, 2021). "Moreover, the frequency of the TNF2(A) allele, which affects plasma TNF levels, is significantly increased in schizophrenia and TNF2 homozygotes are detected in schizophrenia only." (PMID 34831151, 2021).
schizophrenia (continued). "Similarly to our results (concerning rs539689), they found that A allele of the -G308A polymorphism in TNF-α gene increased the susceptibility for schizophrenia only in males." (PMID 31642026, 2020). "Hence, in the subsequent iPSC experiments, we employed lower concentrations, 50 and 250 pg/ml of TNF to assess potential differences in the susceptibility of the control (C) and schizophrenia (SZ) iPSC organoids to TNF." (PMID 33005129, 2020). "A recent meta-analysis found that acute illness in schizophrenia was associated with elevated levels of the peripheral proinflammatory cytokines interleukin (IL) 6 and tumor necrosis factor alpha (TNF-α), and elevated levels of cytokine receptor antagonist (IL-1Ra) and soluble cytokine receptor." (PMID 30918489, 2019). "This higher frequency of the different alleles in male patients, which is known to be associated with increased production of TNFα, might be responsible for the higher prevalence of schizophrenia in male subjects than in female subjects." (PMID 30627222, 2018). "However, the allele frequency of TNF −857T was 16.3% in patients with schizophrenia and 9.8% in the control group, and the difference was statistically significant (p = 0.005/OR = 1.78)." (PMID 30627222, 2018). "TNF-α is a strong candidate gene for schizophrenia susceptibility." (PMID 29317797, 2017). "Single nucleotide polymorphisms have been analysed in many cytokines, in particular, those that are associated with altered levels in schizophrenia such as TNF-α, IL1-β, IL-6, IL-10, INF-γ, and in the genes encoding the immune system regulatory proteins CTLA-4 and CD28." (PMID 29317797, 2017). "Some authors have gone so far as to regard CRP as a causative component of schizophrenia alongside other inflammatory molecules such as IL-8 and TNF-alpha, which may alter neurodevelopment." (PMID 29404313, 2017). "Moreover, inflammation during prenatal and perinatal neurodevelopment, as measured by elevated levels of IL-8 and TNF-alpha in maternal plasma, has been implicated as a risk factor for subsequent development of schizophrenia in offspring." (PMID 29404313, 2017). "Similarly, elevated levels of maternal cytokines, in particular tumor necrosis factor (TNF)α, were associated with increasing odds of adult schizophrenia and other psychoses in their offspring." (PMID 28874190, 2017). "The tumor necrosis factor (TNFα) had been associated with schizophrenia and also it was reported that immune dysregulation could have a genetic component in schizophrenia patients." (PMID 25943100, 2015). "Adolescent Nrg1 HET mice displayed a trend toward increased expression of the pro-apoptotic and inflammatory cytokine TNF-α in the hippocampus and schizophrenia patients with a missense mutation in the transmembrane domain of NRG1 show heightened expression of TNF-α from B cells." (PMID 23447498, 2013). "Abnormalities in the constitutive expression of immunological factors also appear to be involved, in that chronically increased levels of IL-1β, IL-6, IL-8 and TNF-α are positively associated with the severity of the schizophrenia or autism that eventually develops." (PMID 24146637, 2013). "Proinflammatory cytokines especially TNF-α, IL-1ß, and IL-6 exert important roles in mediating acute stress responses and dysregulated production of these cytokines were implicated with chronic CNS inflammation, as well as, schizophrenia." (PMID 22226452, 2012).
schizophrenia (continued). "However, to the best of our knowledge, there is no study investigating sex differences in the association between TNF-α, the OxS system, and their interaction with clinical symptoms in schizophrenia patients, especially in first-episode drug-naïve (FEDN) patients." (PMID 34526062, 2021). "Some studies have proved that heightened stress is immunosuppressive, and thus, the decreased TNF-α and IL-1β in our current study may be caused by stress in first episode schizophrenia, since the experience of acute psychosis in schizophrenia patients is stressful itself." (PMID 29867314, 2018). "Therefore, the overproduction of TNF-α contributes significantly to the pathological complications observed in many inflammatory diseases; for example, pro-inflammatory cytokines can increase the risk of schizophrenia." (PMID 23374533, 2013). "The pro-inflammatory cytokine tumor necrosis factor-alpha (TNF-α) has been reported to be dysregulated in individuals with schizophrenia, but its relationship with brain volume changes remains inconsistent." (PMID 42254729, 2026). "We previously identified IL-6, IL-8, IL-1β, and SERPINA3 mRNAs as the most upregulated inflammation markers in the PFC of schizophrenia cases, whereas the most discriminatory markers in the midbrain also included TNF mRNA." (PMID 41567988, 2026). "Clinical trials with anti-TNF–related biological adjuvants like adalimumab and penfluridol reported improvement of general symptoms in patients with schizophrenia." (PMID 41567988, 2026). "Chronic low-grade systemic inflammation is frequently observed in patients with schizophrenia, with elevated levels of inflammatory cytokines such as interleukin-6 (IL-6), tumor necrosis factor-alpha (TNF-α), and C-reactive protein (CRP)." (PMID 40786633, 2025). "The serum levels of TNF-α in patients with acute relapse of chronic schizophrenia were significantly increased." (PMID 39858450, 2025). "Polymorphisms in immune-related genes, including TNF-α, interleukin-10 (IL-10), and complement C4, have been correlated with increased susceptibility to CMV and increased probability of schizophrenia, suggesting shared pathways in disease aetiology." (PMID 40806558, 2025). "For instance, 6-week treatment with olanzapine reduced proinflammatory cytokines such as IL-1 β, IFN-γ, IL-6 and TNF-α levels, in schizophrenia patients and increased the proinflammatory cytokines such as IL-10." (PMID 39907868, 2025). "By using the Western blot technique, we found notably high concentrations of the inflammatory mediators IL1β, IL-6, and TNF-α in the serum of patients with schizophrenia compared with in the controls." (PMID 41011185, 2025). "The PANSS total scores in schizophrenia displayed moderate-to-strong relations with IL-6 and TNF-α (r = 0.54 and r = 0.48), yet IL-6 and IL-1β exhibited these relations with HAM-D in patients with MDD (r = 0.46 and r = 0.41)." (PMID 40416228, 2025). "PANSS scores in schizophrenia patients correlated with IL-6 and TNF-α serum levels, whereas MDD patients showed correlations between IL-6 and IL-1β levels and HAM-D scores." (PMID 40416228, 2025). "In schizophrenia, IL-6 and TNF-α were positively correlated with PANSS scores while indicating their involvement in symptom severity." (PMID 40416228, 2025). "BDNF binding to TrkBTK- receptors on glia can promote the release of pro-inflammatory cytokines, including IL1β and TNFα, consistent with the increase of these cytokines at the mRNA and protein level we have found in the schizophrenia midbrain." (PMID 40335479, 2025). "Elevated concentrations of cytokines such as interleukin-6 (IL-6), tumor necrosis factor-alpha (TNF-α), and interleukin-1 beta (IL-1β) have been repeatedly observed in individuals with schizophrenia." (PMID 40635756, 2025).
schizophrenia (continued). "The elevation of pro-inflammatorybiomarkers such as IL-6, IL-1β, TNF-α, and CRP has beenassociated with cognitive decline, with this association being particularlypronounced in patients with deficit schizophrenia." (PMID 40926813, 2025). "One of the key inflammatory cytokines implicated in this process is tumor necrosis factor-alpha (TNF-α); the level of TNF-α is altered in patients with schizophrenia." (PMID 38429778, 2024). "Individuals with schizophrenia exhibit elevated pro-inflammatory cytokines (e.g., IL-1β, IL-6, IL-8, and TNF-α) released by the microglia." (PMID 39839138, 2024). "For example, activation of microglia by TNF leads to cortical malformations similar to those observed in the schizophrenia organoids." (PMID 38891836, 2024). "Regarding inflammatory factors, a meta-analysis reported elevated levels of IL-6, IL-1β, and TNF-α in the blood and cerebrospinal fluid of individuals with schizophrenia." (PMID 39324122, 2024). "The causes of PD, ALS, schizophrenia, and HAND arise from vastly different methods, but one of the underlying mechanisms heavily involved appears to include TNF-α." (PMID 38731913, 2024). "Evidence-based studies are representative of altered levels of inflammatory cytokines, including C-reactive protein, IL-1, IL-6, and TNF-α in schizophrenia patients, which affect the basal ganglia and induce negative symptoms." (PMID 39716387, 2024). "In paranoid patients with schizophrenia, TNF-α was negatively correlated with PANSS positive scores." (PMID 38429778, 2024). "The relationship between TNF-α levels and the clinical manifestations of schizophrenia presents a potential avenue for understanding the inflammatory etiology of schizophrenia as well as variations in symptoms." (PMID 38429778, 2024). "In the sole cerebrospinal fluid (CSF) study in the systematic review, CSF TNF was similar in youth with TPD (very early onset schizophrenia) compared to youth with obsessive compulsive disorder and attention deficit hyperactivity disorder." (PMID 38141839, 2024). "The aim of this study was to measure the plasma levels of tumor necrosis factor alpha (TNF-α) and soluble TNF-α receptor 1 (sTNF-α R1) and to investigate their association with agitation in first episode patients with schizophrenia (FEPS)." (PMID 38956509, 2024). "In another study, pathologically higher levels of IL-1β and TNF-α serum, along with NF-κB activation, were found in schizophrenia patients compared to healthy individuals." (PMID 39766497, 2024). "NCE considerably decreases the malondialdehyde (MDA) and DA levels and IL-6 and TNF-α expressions in mice with schizophrenia-like symptoms." (PMID 38371525, 2024). "NFκB is a master immune transcription factor, which regulates inflammatory cytokines, including IL-1β, IL-6, and TNFα, and is involved in the pathogenesis of schizophrenia." (PMID 39769285, 2024). "Based on the results of this study, it is suggested that T. gondii-mediated increased IL-1β, TNF-α expression and NF-κB activation in the brain contribute to the pathogenesis of schizophrenia." (PMID 39766497, 2024). "A previous study found that TNF-α levels were higher in first-episode drug-naive (FEDN) patients with schizophrenia than those in healthy controls." (PMID 38956509, 2024). "The major role of TNF-α in the pathophysiology of schizophrenia at various stages has been reported several times in previous studies, including in animal models." (PMID 38429778, 2024). "For example, a meta-analysis of cytokines in schizophrenia found higher levels of pro-inflammatory cytokines such as IL-6, TNF-α and sIL-2R in acute patients, and IL-6, IL-1β and sIL-2R in chronic patients than in healthy controls." (PMID 38352871, 2024). "Plasma TNF-α levels were significantly elevated in patients with early-onset schizophrenia (12–20 years old) compared with healthy subjects." (PMID 38956509, 2024).